INS (insulin)
Diseases named in the same sentence as INS in open-access papers (continued):
Sharing a sentence is not in itself a finding about the gene and the disease.
diabetes (continued). "We investigated the effect of hypoglycemia in the setting of acute glycemic fluctuations on cardiac rhythm and cardiac repolarization in insulin-treated patients with type 2 diabetes compared with matched controls without diabetes." (PMID 34085953, 2021). "Decreased body weight, fasting blood glucose and basal insulin levels were confirmed, which showed that CCE could relieve diabetes-related symptoms." (PMID 33435282, 2021). "Current treatment for diabetes included 2 patients on diet alone, 9 on noninsulin antihyperglycemic medications, and 22 on insulin or a combination of insulin and other antihyperglycemic agents." (PMID 33334148, 2021). "Moreover, in patients with diabetes, the RAS promotes decreased insulin secretion and sensitivity, as well as the progression of diabetic cardiovascular complications." (PMID 34068221, 2021). "It has been well-documented that insulin clearance is lower in states of obesity, prediabetes, and diabetes; however, most studies reporting this did not attempt to adjust for effects of insulin sensitivity or insulin secretion." (PMID 34206745, 2021). "In 23.0% of the experiments involving people with diabetes, an overnight low-dose insulin infusion was provided to normalise glucose levels prior to the clamp." (PMID 33566134, 2021). "Importantly, from a real-world primary care diabetes care management perspective, in this study the average daily frequency of FSBG checks was low, despite 40% of the participants being on insulin by the end of the intervention." (PMID 34758807, 2021). "Management of targeted treatment-related type 2 diabetes mellitus includes diet, exercise, oral hypoglycemic agents with or without insulin." (PMID 34830886, 2021). "Among diabetes-specific clinical variables, we observed that HbA1C levels (at baseline) influenced the participants’ SG values during TE#1 and TE#2 exercise sessions, whereas diabetes duration and insulin dose regimen did not." (PMID 34512541, 2021). "The first evaluation conducted by the Ministry of Health concluded that there was no robust evidence that they were more effective than human insulin for the control of diabetes." (PMID 33967753, 2021). "Yet, we are not aware of prior data using human brain tissue from persons with and without diabetes, which examines the relation of brain insulin signaling or resistance to cerebrovascular disease." (PMID 33858515, 2021). "Even with such exclusion, on top of insulin exclusion and for both reports with and without the diabetes indication, disproportionality remained robust and significant." (PMID 33573667, 2021). "Results of Cox regression analyses are presented without and with adjustment for confounding factors (age, diabetes status, fasting insulin, smoking, BMI, LDL-C, HDL-C, statin treatment, drug treatment for hypertension, and hs-CRP)." (PMID 34346487, 2021). "T1DM is mainly diagnosed in children and referred to as juvenile diabetes, which can develop at any age, while Type 2 diabetes mellitus (T2DM) is thought to occur in its earliest phase, from the declining sensitivity of peripheral tissues to circulating insulin." (PMID 33747345, 2021). "This retrospective cohort study assessed patients 65 years and older with diabetes not taking insulin who were hospitalized in the Veterans Health Administration Health System between January 1, 2011, and September 28, 2016, for common medical conditions." (PMID 34673963, 2021). "Our data, clarifying and confirming the protective anti-inflammatory and insulin-sensitizing mechanisms of NMP, suggests the need for and the potential utility of further testing this molecule in pre-clinical animal models of obesity and diabetes." (PMID 34680177, 2021). "Diabetes mellitus (DM) is a metabolic disorder regulated by a glucose-lowering hormone known as insulin produced by pancreatic β-cells; the release of insulin is not adequate, which results in DM." (PMID 33803178, 2021).
diabetes (continued). "Nonetheless, these studies suggest that combining insulin sensitizer and GLP-1RA therapies may better improve diabetes and fatty liver disease and potentially attenuate TZD-induced weight gain." (PMID 34022222, 2021). "Particularly, PTP1B is involved in the regulation of insulin signaling in the absence of insulin stimulation and its specific inhibition turned out to be essential for treating diabetes." (PMID 34067862, 2021). "Diabetes is a chronic disease condition that develops when the pancreas no longer produces insulin or when the body does not utlize the produced insulin properly." (PMID 34683861, 2021). "The impaired capacity of the liver to synthesize glycogen was observed in diabetes due to lack of insulin." (PMID 34504420, 2021). "We explored the cascade effects of a high fat-carbohydrate diet (HFCD) and pioglitazone (an anti-diabetic therapy used to treat type 2 diabetes mellitus (T2DM)) on lipid profiles, oxidative stress/antioxidant, insulin, and inflammatory biomarkers in a rat model of insulin resistance." (PMID 34037093, 2021). "One of the “secondary” effects of ACEI is an amplification of insulin sensitivity and glucose tolerance in patients with insulin resistance in such an efficient manner that some ACEI were proven to prevent the development of type 2 diabetes mellitus." (PMID 34575946, 2021). "This study did not classify diabetes pharmacological regimen as a whole but ADA to insulin changes separately." (PMID 34116645, 2021). "At the baseline visit, compared to individuals who did not develop the outcome, those who developed had a longer duration of diabetes, higher BMI, WHR, WHtR, waist and VAI, worse glucose and lipid control, lower eGFR and insulin sensitivity, despite similar blood pressure and distribution of sex." (PMID 34315479, 2021). "In this review, we cover the interactions of oxidative stress at the BBB, how insulin signaling is related to oxidative stress, and the impact of the BBB in two diseases greatly affected by oxidative stress and insulin resistance: diabetes mellitus and Alzheimer’s disease." (PMID 34829566, 2021). "The ability of T2DM patients to produce insulin in the body is not completely lost, and this type of diabetes treated with certain oral drugs that stimulate insulin secretion in the body." (PMID 34539410, 2021). "CYP8B1 was one of the key enzymes of bile acids synthesis, and ablating CYP8B1 in mice led to reduced absorption of dietary triglyceride with intact triglyceride hydrolysis and improved insulin sensitivity, suggesting CYP8B1 as a potential therapeutic target for obesity and diabetes." (PMID 33980183, 2021). "Diabetes is a disease with a high concentration of glucose in the blood due to a lack of insulin secretion or poor functioning." (PMID 34684679, 2021). "The present study was done as sequelae to our clinical study which showed a high association between coronary artery disease and high insulin resistance and high fasting plasma insulin even in the absence of hyperglycemia or diabetes." (PMID 33708999, 2021). "Type 2 diabetes mellitus (T2DM), is a chronic metabolic pathology, characterized by abnormalities in glucose clearance with chronic hyperglycemia and insufficient response to insulin, i.e., insulin resistance." (PMID 34501954, 2021). "Despite these limitations, this study does provide insight into the association between fasting insulin and CRP in adults without diabetes." (PMID 33691751, 2021). "There is evidence that insulin-induced increase in the expression of steroidogenic enzymes, reduced in severe, insulin-deficient STZ diabetes, does not lead to the normalization of steroidogenesis." (PMID 35008624, 2021). "There is no universal approach to insulin dosing, or to diabetes management, due to the substantial variation that occurs within and between individuals." (PMID 34836409, 2021).
diabetes (continued). "The use of insulin analogs, insulin pumps, and continuous glucose monitoring (CGM) systems has made physical activity, including school, recreational, and professional sports, more common among diabetics." (PMID 33801780, 2021). "While we have used parameter estimates specific to insulin whenever available, when missing, we used estimates based on all diabetes drugs, or, lacking those, on all brand-name drugs." (PMID 35977268, 2021). "In 1967, Perley and Kipnis observed that, in response to either oral or IV glucose, plasma insulin was higher in obese versus normal weight individuals without diabetes." (PMID 34822454, 2021). "Because no real cure exists for diabetes, daily insulin injections remain the standard of care for patients with T1D, late-stage T2D, and for a subset of patients with monogenic diabetes." (PMID 33477961, 2021). "The Therapeutic Goods Administration (TGA) responded on 19 March by limiting pharmacies to dispense a one-month supply of both insulin and non-insulin diabetes medicines regardless of Regulation 49 prescriptions." (PMID 34209616, 2021). "Diabetes is a serious chronic disease that occurs when the body cannot produce or does not make enough insulin or cannot use what it does effectively." (PMID 34924860, 2021). "When the compensatory increase of insulin production can no longer compensate for IR, blood sugar rises and the insidious process leading to type 2 diabetes mellitus begins." (PMID 34681797, 2021). "After ingesting a meal, healthy adults show increased insulin secretion and suppressed glucagon secretion, whereas people with diabetes do not show suppression of glucagon secretion." (PMID 34199839, 2021). "Accordingly, the approach treating diabetes by pharmacological inhibition of IDE, predicated as it is on increasing circulating insulin levels by slowing insulin clearance, will require more thorough investigation of this topic to assess the wisdom of this approach." (PMID 33668109, 2021). "Most likely, the provided data, even with the huge number of readers, do not represent the majority of patients with diabetes requiring insulin therapy in Poland." (PMID 33794101, 2021). "In the diabetics, the number of TNFα gold labels is significantly increased in the duodenum, decreased in the colon and remained unchanged in the ileal ganglia, while insulin does not prevent these diabetes-related TNFα changes." (PMID 34572059, 2021). "After four weeks of diabetes, insulin levels were not significantly different between the experimental groups." (PMID 34202017, 2021). "In people without diabetes, insulin secretion decreases, resulting in an increase in the glucagon:insulin ratio and increased hepatic glucose production, precisely matching the increased glucose utilization by muscles." (PMID 34444464, 2021). "Before the twentieth century, insulin was not available, so scholars advocated the “starvation diet” to treat diabetes mellitus (DM); it was considered the only method to solve hyperglycemia." (PMID 34970224, 2021). "Insulin sensitivity has been improved by another TNF-α inhibitor adalimumab in psoriasis patients without diabetes." (PMID 34803716, 2021). "Risperidone treatment offers protective benefits compared with medications, such as olanzapine, which can exacerbate diabetes mellitus or increase insulin secretion patients with schizophrenia who do not have diabetes but exhibit signs of hypoglycemia." (PMID 33401717, 2021). "Reduced replication fork speed during differentiation improved the stability of insulin expression, and the resulting cells protected mice from diabetes without the formation of cystic growths." (PMID 33529174, 2021). "Participants who were prescribed insulin were younger and had lower BMIs, longer durations of diabetes, and worse glycemic control than those who were not prescribed insulin as their initial medication." (PMID 33502325, 2021).
diabetes (continued). "The 301 individuals with insulin-treated diabetes and one or two DR15-DQ6 haplotypes had a similar mean non-HLA T1DGRS and a similar T2DGRS to individuals with type 2 diabetes (each p > 0.1)." (PMID 34272580, 2021). "Aside from acute consequences of caffeine intake there were no consistent effects on diabetes-relevant metabolic parameters such as the insulin and glucose response to a glucose load or to a meal." (PMID 33807132, 2021). "Few published data are available on the relation of brain insulin signaling and resistance in persons with and without diabetes, to cerebrovascular pathology." (PMID 33858515, 2021). "Diabetes is characterized by complete or partial lack of insulin, which leads to elevated blood sugar (glucose) levels and the overall prevalence of diabetes has been estimated to be about 8% of a population." (PMID 34828602, 2021). "Meanwhile, as a positive control, rosiglitazone, a thiazolidinedione-type medicine for treating diabetes, also promoted the glucose consumption of the cells in the presence or absence of insulin (Groups 7 and 8)." (PMID 33746602, 2021). "extracts to control diabetes, the inhibitory activities of α-glucosidase, the carbohydrate degrading enzyme, and dipeptidyl peptidase-IV (DPP-IV), the enzyme that controls the release of insulin, were examined." (PMID 33670795, 2021). "The rationale of performing non fasting OGTT is that, normoglycaemic women usually have normal insulin response when given glucose load, whereas a pregnant woman with diabetes will not be able to maintain euglycemia post meals and after glucose load." (PMID 34290774, 2021). "Fourth, measurements for severity of diabetes and insulin dosing used during hospitalization were not available in our databases, and thus, the analyses did not adjust for diabetes severity or duration." (PMID 34277991, 2021). "Diabetes is a pathology characterized by hyperglycemia resulting from a total or partial lack of insulin." (PMID 33572056, 2021). "This Bla.C treatment suggests that plasma insulin and HOMA-IR reduction and improved glucose tolerance may improve insulin resistance in diabetes." (PMID 34836432, 2021). "KATP channel blockers such as sulfonylureas, insulin secretagogues, have been widely used to treat diabetes for over 60 years without pro-diabetic effects." (PMID 34556670, 2021). "Results suggest that dysfunctional PVAT contributes to vascular pathology induced by altered insulin signaling in diabetes, in the absence of fat overload and obesity." (PMID 34207844, 2021). "Both study arms, which included only diabetes-free men, differed in baseline values of HOMA1-IR and this finding is in line with the previous observations indicating that male siblings of PCOS probands are characterized by impaired insulin sensitivity." (PMID 32696349, 2021). "Diabetes is one of the most common chronic metabolic disorder diseases in the worldwide, over 90% of the diabetes patients are type 2 diabetes mellitus (T2DM), which is characterized by insulin resistance in peripheral tissues and dysregulated insulin secretion by pancreatic beta (β) cells." (PMID 34880907, 2021). "Patients also expressed feeling stigmatised at having to take long term medications (particularly insulin for diabetes) with resultant anxiety, although this did not lead to treatment default." (PMID 33503044, 2021). "The predictors for higher baseline A1C are non-Chinese ethnicity, younger age groups, longer diabetes duration, treatment with insulin, polypharmacy use, without hypertension and not on antihypertensive agents." (PMID 33762665, 2021). "In that case, SLC2A4 expression level has no prognostic level for cancer outcome but diabetes and increased insulin secretion have." (PMID 34488531, 2021). "Diabetes is a chronic condition that occurs when the body either does not produce enough insulin or cannot effectively use the insulin it does produce." (PMID 34490230, 2021).
diabetes (continued). "The causes of diabetes are diverse and eventually lead to absolute or relative lack of insulin, which leads to diabetes." (PMID 34028177, 2021). "Current treatments for diabetes, despite their great beneficial effects on clinical symptoms, are not curative treatments, leading to a chronic dependence on insulin throughout life that does not prevent the secondary complications associated with diabetes." (PMID 33921851, 2021). "Diabetes incidence was defined as fasting glucose ≥126 mg/dl or nonfasting glucose ≥200 mg/dl; reported use of insulin or oral hypoglycemic medication; or documentation of diabetes diagnosis through the Centers for Medicare and Medicaid Services records." (PMID 34555371, 2021). "For our participants who had severe obesity but were otherwise clinically healthy, it was difficult from meal test data to compare capacities for insulin secretion when blood glucose levels were as expected in subjects without diabetes." (PMID 33684170, 2021). "Exercise activates AMPK, which in turn enhances glucose uptake into muscle and improves insulin sensitivity thus helping to offset the negative effects of obesity, diabetes and cardiovascular disease and thereby reducing morbidity and improving healthspan." (PMID 34421827, 2021). "Moreover, it is suggested that a high proportion of fat in the diet is associated with impaired insulin sensitivity and an increased risk of developing diabetes, independent of obesity and body fat localization; moreover, this risk may be influenced by the type of fatty acids in the diet." (PMID 33613155, 2021). "Insulin-treated women without family diabetes history and women on diet with pre-pregnancy BMI > 28.1 kg/m2 showed a two-fold PPD risk." (PMID 33842997, 2021). "The HOMA model is an easy method for evaluating insulin sensitivity, and it is connected with the results of the glucose clamp test in patients with mild diabetes without hyperglycemia." (PMID 34209501, 2021). "LGI diets aim to flatten the postprandial blood glucose and insulin curves, and their positive effect has been proved in obesity, diabetes, and other non-communicable diseases." (PMID 34444964, 2021). "Both patients with WSS that we reported had diabetes in young adulthood with reduced insulin and C-peptide levels, negative insulin-related antibodies, and pancreatic atrophy from abdominal CT." (PMID 35002959, 2021). "Compared to patients with prior CVD, those with diabetes only not taking insulin had a lower risk for CVD events (HR: 0.84; 95% CI 0.82, 0.87), while patients with diabetes only taking insulin had a higher risk for CVD events (HR: 1.20; 95% CI 1.15, 1.25)." (PMID 33648518, 2021). "Diabetes mellitus (DM) is a metabolic disorder in which the body either does not produce sufficient amounts of insulin, has impaired insulin action or a combination of the two." (PMID 34884494, 2021). "In contrast, in people without diabetes, insulin secretion decreases during exercise and the secretion of counter-regulatory hormones, which increase the production of glucose by the liver, balances the glucose uptake by skeletal muscles during exercise." (PMID 33467392, 2021). "Diabetes mellitus (DM) represents a heterogeneous group of chronic metabolic diseases manifested clinically by hyperglycaemia due to lack of insulin secretion, function or both." (PMID 34940355, 2021). "Regarding diabetes, 481 (20.2%) were on oral medical therapy, 144 (6.1%) were on insulin, 40 (1.7%) were on oral medication and insulin, and 46 (1.9%) were not taking their medication." (PMID 35620276, 2021). "The type of CCD used was not statistically different between patients without diabetes vs. patients with diabetes taking insulin (p = NS)." (PMID 34044894, 2021). "SRA1 expression associated with BMI, PBF, serum insulin, and HOMA-IR in the total study population and people without diabetes." (PMID 34685582, 2021).